INS (insulin)
Diseases named in the same sentence as INS in open-access papers (continued):
Sharing a sentence is not in itself a finding about the gene and the disease.
insulinoma (continued). "SUR1 and Kir6.2 expression was found in the three insulinomas examined indicating that unregulated insulin secretion by these tumors does not result from failure to express one or both KATP channel subunits." (PMID 16266437, 2005). "Unfortunately, little has been reported about KATP channel mutations in human insulin producing tumors and the authors are not aware of any reports examining the KATP channel in canine insulinoma." (PMID 16266437, 2005). "KATP channel subunit expression was detected in all three canine insulinomas examined, indicating that absence of subunit expression cannot account for the abnormal insulin secretion observed with these tumors." (PMID 16266437, 2005). "The islet origin of canine insulinomas is further supported by our findings that these tumors also express glucokinase and insulin but not amylase (V. Donley and T. Schermerhorn, unpublished observations)." (PMID 16266437, 2005). "All NESP55-expressing endocrine pancreatic tumours were insulin-producing (1 malignant and three benign insulinomas), while all NESP55-negative tumours were nonfunctioning malignant tumours." (PMID 12771991, 2003). "Somatostatin receptor (SSTR)-targeted imaging is also an option; however, it is less sensitive in diagnosing insulinomas compared with other pancreatic neuroendocrine neoplasms and does not provide information on its endocrine function, such as insulin secretion." (PMID 40405975, 2025). "Our data showing reduced CaSR expression in insulinomas would suggest that insulin secretion is not dependent on CaSR signalling, and therefore, the CaSR may be playing additional roles in these tumours." (PMID 39579056, 2025). "Therefore, positive insulin staining is not obligatory for diagnosing insulinomas and is typically not required once the clinical diagnosis has been established." (PMID 39968426, 2025). "Calcium gluconate acts as an insulin secretagogue, stimulating insulin release specifically from insulinomas or areas of islet cell hyperplasia but notably not from normal β cells where the glucose and insulin levels remain unchanged with calcium gluconate infusion." (PMID 40799776, 2025). "However, adropin administration did not affect serum insulin levels in diabetic rats or insulin release from INS-1 832/3 rat insulinoma cells and pancreatic tissue fragments." (PMID 39337311, 2024). "The remaining subjects negative for insulinoma had a significantly higher baseline glycaemia, with average 78.53 ± 14.04 mg/dL (range 58–119) (p < 0.001) along with lower insulin (mean 5.15 ± 3.6 μU/mL, p = 0.055) and significantly lower C-peptide (1.51 ± 0.66 ng/mL, p = 0.023)." (PMID 38451386, 2024). "The expression of ATP6AP2 proteins was clearly detected in insulin-expressing cells of normal islets near the insulinoma lesions and nonfunctioning NETs, whereas it was not or faintly detected in glucagon-expressing cells and somatostatin-expressing cells in the same regions." (PMID 37286698, 2023). "In a patient with documented endogenous hyperinsulinemic hypoglycemia, negative screening for oral hypoglycemic agents, and no circulating insulin antibodies, the hypothesis of an insulinoma should be considered." (PMID 37308982, 2023). "Therefore, the negative correlation of UPRmt with insulin expression is likely true in mouse islet cells, lending further support to our observations in the insulinoma β-cells." (PMID 37758822, 2023). "Therefore, we logically assume that the heterogeneous expression of ion channel-related genes between insulinoma and NFPNET may contribute to the heterogeneity ability of insulin secretion." (PMID 37772258, 2023). "Therefore, in this present study, we utilized a differentiated mouse insulinoma cell line NIT-1 to determine the direct effect of ADM on β-cell growth and insulin secretion and synthesis and investigate the mechanisms of ADM action on β-cell growth and function." (PMID 35324977, 2022).
insulinoma (continued). "In addition, risk assessment is also done based on the presence of plasma autoreactive antibodies (autoantibodies) against β-cell antigens such as, pro-insulin and insulin, glutamic acid decarboxylase (GAD), tyrosine phosphatase present in insulinomas (anti-IA2), and Zinc transporter 8 (ZnT8)." (PMID 33806609, 2021). "A key unanticipated finding is that the 19 insulinomas differ from the five beta-cell data sets with regard to the methylation status of the INS region, where the key beta-cell transcription factor, PDX1, binds, recruits other enhancer members, and transactivates INS gene expression." (PMID 33060578, 2020). "INS can increase as a consequence of several oncologic and non-oncologic conditions, therefore, its concentration alone does not represent a solid marker for insulinoma." (PMID 32537434, 2020). "Moreover, miR-9 has been implicated in insulin secretion and has been proposed to be regulated by HG levels in pancreatic beta-cells (insulinoma), and recent works show that miR-9a regulates body growth by controlling sNPFR1/NPYR-mediated modulation of insulin signaling." (PMID 30965609, 2019). "In addition to demonstrating in vitro cAMP activity at human and mouse GLP-1R in transfected CHO and in the mouse MIN6 insulinoma cells, MEDI4166 induced glucose-stimulated insulin secretion in INS1 β-cells and displayed a desirable profile in rodent disease models." (PMID 30510163, 2018). "Recently, we showed using Ca2+-microelectrodes that stimulation of insulin secretion by high glucose and other secretagogues (glibenclamide, forskolin/IBMX, and ATP) induced a delayed elevation of extracellular Ca2+ within rat insulinoma (INS-1E) β-cell pseudoislets." (PMID 29584660, 2018). "Human insulinomas do not retain normal control of glucose sensing and insulin secretion." (PMID 28974674, 2017). "In a separate report, a 96-h, 0.25-μM iAsIII treatment of a rat insulinoma (INS-1-832/13) cell line was shown to induce a significant Nrf2-mediated antioxidant response, which suppresses endogenous reactive oxygen species that are thought to be involved in insulin secretion." (PMID 28275977, 2017). "Lastly, to confirm the relationship of insulin production with autophagy and EDC3 protein, we investigated whether the mTOR inhibitor, rapamycin, induced autophagy and expression of GRP78/BiP and EDC3 proteins in rat insulinoma INS-1E cells." (PMID 27493704, 2016). "Furthermore, the autophagy inhibitors, bafilomycin A1 and/or 3-methyladenine, in the presence or absence of 2-DG or rapamycin increased intracellular insulin in INS-1E insulinoma cells." (PMID 27536716, 2016). "This underlines that the drug may be effective in the management of insulinoma irrespective of its antineoplastic activity and its effect on insulin production." (PMID 25298880, 2014). "A diagnosis of insulinoma was ruled out by examining the insulin level." (PMID 25202415, 2014). "In an insulinoma cell line and in pancreatic β cells, Sx 4 facilitates secretion of insulin over expression of Sx 1A and Sx 3 but not Sx 2 and Sx 4, strongly inhibited actions on insulin release." (PMID 18060067, 2007). "Likewise, these methods could also be used to learn more about canine insulinoma, in particular the contribution of abnormal KATP channel function to the unregulated insulin secretion that characterizes these tumors." (PMID 16266437, 2005). "Secondly, the metastatic insulinoma lesion, found in the abdomen attached to the peritoneum, contained all the different cell types represented in the primary tumour, rather than presenting as a single population of neoplastic insulin-expressing endocrine cells." (PMID 40438247, 2025). "Thus, GLP-1R-positivity is not restricted to insulinoma or insulin IHC-positive pNETs." (PMID 41312422, 2025).
insulinoma (continued). "In the NIH series of studies on insulinoma, the researchers proposed to increase the insulin and proinsulin thresholds to 5 μIU/ml and 22 pmol/L, respectively, leading to higher specificity of 98% and 100% but lowering the sensitivity for insulin to 91%, regardless of the blood glucose level." (PMID 36339408, 2022). "Consistently, another report has shown that isorhamnetin and a glycosylated form of isorhamnetin (isolated from Salicornia herbacea plant) could promote glucose-stimulated insulin secretion in insulin-secreting rat insulinoma (INS-1) pancreatic β-cells without affecting cell viability." (PMID 35054888, 2022). "In addition, in order to ensure complete resection of insulin-secreting tissue, or to ensure that another tumour location of the insulinoma is not overlooked, some authors have proposed intraoperative monitoring of insulin level using a rapid insulin immunochemiluminescent assay." (PMID 34885079, 2021). "However, it remains unclear whether the 11p15 events are specific to insulinomas, or whether they might apply to all PNETs, most of which do not produce or secrete excessive amounts of insulin." (PMID 33060578, 2020). "Moreover, knockdown of IRE1α in INS-1 insulinoma cell line resulted in decreased proinsulin biosynthesis or insulin content without impacting global protein synthesis or insulin secretion, suggesting a beneficial effect of IRE1α activation by transit exposure to glucose in β cells." (PMID 24812634, 2014). "In this study, we show that MRPS6 but not SLC5A3 regulates glucose-stimulated insulin secretion (GSIS) in primary human β-cell and a mouse pancreatic insulinoma β-cell line." (PMID 37758822, 2023). "For these four patients, the proinsulin/insulin molar ratio <1 and primary tumors were all present as PDX1+, ARX-, and insulin+, which were similar to non-metastatic insulinomas." (PMID 37251916, 2023). "In the RINm5F insulinoma cell line, GAL inhibited the activity of AC and moderately suppressed the accumulation of insulin, but did not affect cell proliferation; Gi3, a G protein coupled to GALRs, was involved in this inhibition." (PMID 35954419, 2022). "Insulin, glucagon, ARID1A, H3K36me3 IHC, and CDKN2A FISH were only tested on 31 cases, as for the last four insulinoma cases, no unstained TMA slides were available." (PMID 32103422, 2020). "Chronic exposure to the different metabolic stresses, known to alter glucose-stimulated insulin secretion, did not change AMPK expression, either in insulinoma cells or in human islets." (PMID 32492936, 2020). "While Grb10 knock-down in the rat insulinoma cell line INS-1 lacking glucagon resulted in marked reduction of insulin, GRB10 knock-down in human pancreatic islets resulted in reduction in both insulin and glucagon secretion and expression." (PMID 24699409, 2014). "This plasmid was transiently transfected into human fibroblasts (a non-insulin-producing negative control), as well as in HIT-T15 cells and the rat insulinoma cell line, INS-1 823/13." (PMID 22530041, 2012). "Furthermore, as GLP- 1R-positive patients showed significantly higher expression of insulin and proinsulin than GLP- 1R negative patients, GLP- 1R may also be associated with neoplastic insulin production and GLP- 1 analog scintigraphy may detect subclinical insulinomas." (PMID 40281248, 2025). "However, while capsaicin also stimulates insulin secretion in minced pancreas samples and RIN insulinoma cells it was without effect on non-selective cationic currents in primary rat β-cells and failed to increase calcium in primary rat and human β-cells." (PMID 31925452, 2020). "If excessive insulin secretion is confirmed, but ASVS yields negative results in all areas of the pancreas, there may be an ectopic insulinoma." (PMID 31743337, 2019).
insulinoma (continued). "These putative relationships were explored further in rodent BRIN-BD11 insulinoma cells; while human pancreatic islets and β-cells are known to express CYP27A1, rodent insulinoma cells do not, indicating that this protein is not an essential requirement for glucose-stimulated insulin secretion." (PMID 30819824, 2019).
depression (653 papers, 2006 to 2026). "Aberrant insulin signaling has been associated with mood disorders like depression, as evidenced by animal models exhibiting behaviors resembling depression, which can be ameliorated through insulin therapy." (PMID 40927563, 2025). "In this study, we found a statistically significant correlation between depression and the type of diabetic medications used, with insulin usage being associated with higher levels of depression." (PMID 40355242, 2025). "CRS induced significant psychological and physiological changes in mice, including depression-like behaviours, weight loss and reduced insulin sensitivity." (PMID 40148860, 2025). "Research has identified T2DM-related risk factors, such as insulin dependency, as significant contributors to the development of depression and anxiety." (PMID 40135018, 2025). "Overall, these results underline the importance of considering depression when selecting antidiabetic treatments, as it appears to influence both medication choices and insulin therapy intensity." (PMID 40429455, 2025). "Specifically, age, sex, race and ethnicity, PIR, cost-related medication/insulin underuse, self-reported health, diagnosed depression, and diagnosed anxiety were significantly associated with DD (P < .05)." (PMID 39993145, 2025). "Our findings suggest a notable association between insulin use and depression, even among patients with apparently good glycemic control." (PMID 40429455, 2025). "Treatment Regimen: Insulin use—especially combined oral and insulin therapy—was associated with higher depression risk." (PMID 41189617, 2025). "Among females with EC and BMI ≥ 30 kg/m2, healthier lifestyle patterns were associated with better QoL and insulin sensitivity, but also higher anxiety and depression." (PMID 41431696, 2025). "The patient was a 53-year-old man with a history of depression, anxiety, heterozygous MTHFR mutation, type 1 diabetes on insulin, sleep apnea, and mild cognitive impairment who presented to the outpatient psychiatry clinic for depression and ADHD." (PMID 40291316, 2025). "Second, weight loss improves insulin sensitivity and increases brain-derived neurotrophic factor, supporting neurotransmitter function and reducing depression risk." (PMID 41311799, 2025). "Mechanistically, physical activity reduces systemic inflammation, improves insulin sensitivity, and optimizes body composition—all factors that decrease the risk of both oncogenesis and depressive disorders." (PMID 41409248, 2025). "Insulin plays a role in modulating reward behaviors, and various brain regions sensitive to insulin are linked to depression development." (PMID 38892598, 2024). "An illustration of this intricate relationship is the reported observation that individuals who are obese and insulin-resistant are more susceptible to major depressive disorders (MDD) compared to their healthy counterparts." (PMID 39596474, 2024). "Our findings further strength this association by discovery of both potassium channel gene sets and insulin secretion gene sets in association of depression and anxiety score." (PMID 38827440, 2024). "For example, insulin inactivation was associated with food addiction, which can affect adherence to a healthy lifestyle, as well as increase the risk of depression." (PMID 38321471, 2024). "At the same time, those who were on both insulin and diabetic medications were approximately 5.73 times higher risk of depression (aOR = 5.73; 95% CI: 1.78–18.45, p = 0.003)." (PMID 37237354, 2023). "Significant weight loss, along with improvements in postprandial insulin levels and depression, suggests that such interventions can positively affect the physical and psychological symptoms of individuals with PCOS." (PMID 37511908, 2023). "Insulin users (aOR = 1.86, 95% CI: 1.02–3.42, P = 0.044) were at an increased risk of comorbid depression." (PMID 36918821, 2023).
depression (continued). "Regarding treatment with insulin, both our study and the recent study from Qatar28 showed that patients with Type 2 DM who were treated with insulin had a lower risk for developing depression than other patients." (PMID 39035064, 2023). "In the present study, 75.40% of the participants were treated with insulin, and this group had a 1.86-fold risk of developing depression compared with their counterparts." (PMID 36918821, 2023). "Akt is involved in peripheral glucose uptake and insulin sensitivity; moreover, Akt signaling in the brain is associated with depression." (PMID 37664431, 2023). "Insulin treatment strategies, regular physical activity, and social support were independently associated with depression." (PMID 36918821, 2023). "PO: weight loss and HbA1c SO: fasting lipids, glucose, and insulin concentrations; BP; dietary assessment; physical activity measurements; and quality of life and depression scores." (PMID 37724711, 2023). "Chronic activation of the amygdala in the brain, which is primarily associated with emotional processes and depressive disorders, has been reported to induce inflammation, insulin sensitivity and eventually CVD." (PMID 37529617, 2023). "In sum, research indicates that insulin, leptin, and adiponectin are linked to inflammation, reward signaling, and depression, but it is still unclear how these hormones relate to altered brain reward processing in MDD as a function of inflammation." (PMID 37443383, 2023). "On the other hand, depression is linked to low vitamin D levels, hypercortisolemia and alteration of other hormone concentrations (e.g., estrogen, testosterone, insulin growth factors), which are key regulators in bone formation and bone resorption." (PMID 35413849, 2022). "HG itself is associated with higher blood pressure in children age 5–6 years which is coupled with lower insulin sensitivity and elevated cortisol concentrations and greater risk of neuropsychiatric disorders including depression, bipolar disorder and anxiety." (PMID 35271586, 2022). "Persistently high fasting insulin levels from age 9 years were associated with psychosis at 24 years, and puberty-onset body mass index increase was associated with depression at 24 years." (PMID 33439216, 2021). "The research results are helpful for studying the association between depression and insulin and helping follow-up researchers to determine journal publications and collaborators." (PMID 34366917, 2021). "Articles on the association between insulin and depression have been published in 1,125 different journals." (PMID 34366917, 2021). "Seventy-five countries or regions have contributed to publications in the field of research on the association between depression and insulin." (PMID 34366917, 2021). "As far as we know, this study is the first one to visualize the association between depression and insulin and predict potential future research trends through bibliometric and visual analysis." (PMID 34366917, 2021). "This study is based on bibliometric analysis and systematically evaluated the association between insulin and depression through 3,131 publications of Web of Science from 2010 to 2020." (PMID 34366917, 2021). "The MYRIP gene is also reported to have a role in insulin secretion and low insulin levels have been linked to depression." (PMID 35069690, 2021). "It was reported previously that depression is linked to blood insulin tested at 2 h in a glucose tolerance test." (PMID 34744814, 2021). "Are longitudinal trends in insulin levels and body mass index from childhood associated with adult depression and psychosis?" (PMID 33439216, 2021). "Investigate the output and growth trends of publications in the field of the association between insulin and depression." (PMID 34366917, 2021). "We found that depression was associated with worse glycaemic control and being on insulin treatment—in essence a poor prognostic group." (PMID 32566681, 2020).